FGFR1 (fibroblast growth factor receptor 1)
Diseases named in the same sentence as FGFR1 in open-access papers (continued):
Sharing a sentence is not in itself a finding about the gene and the disease.
tumor (continued). "The incidence of FGFR1-4 genomic alterations across different tumor types and the genomic comutational landscape influencing the response to FGFR inhibitors should be studied in a broad manner." (PMID 36462464, 2022). "In particular, FGFR1 is highly activated in nearly 80% of ES samples, probably promoting tumor progression and dissemination by activating the PI3K/AKT, RAS/MAPK, and JAK/STAT signaling pathways." (PMID 36430263, 2022). "Two patients with FGFR3-amplified Sq-NSCLC have been reported: one with tumor shrinkage by 25% and the other (with concomitant FGFR1 amplification) with a 10% increase in tumor size." (PMID 35402233, 2022). "FGFR1–3 protein overexpression was detected both in the cytoplasm and cell membrane in 5 of 18 (27.7%) tumor samples." (PMID 36142417, 2022). "In conclusion, we comprehensively surveyed the pan-tumor landscape of FGFR1-4 genomic alterations in this study and identified a number of co-occurring and mutually exclusive alterations in other genes, as well as associations with the genomic signature TMB." (PMID 36462464, 2022). "The nuclear FGFR1 can also promote the transcription of ER-targeting genes and cell proliferation; thus, FGFR inhibitor plus fluvestrant show potent anti-tumor effect in ER-positive and FGFR1-amplified cancer cells." (PMID 36518248, 2022). "The targets of action of anlotinib include VEGFR2/3, PDGFRα/β associated with tumor vascular survival ability (VSA), and FGFR1-4 associated with fibrosis." (PMID 35847852, 2022). "FGFR1 promotes tumor growth and proliferation by activating growth and nutrient signaling via PI3K and mTOR activation." (PMID 35626002, 2022). "Gain- or loss-of-function experiments revealed that the bevacizumab-resistant tumor cell–derived FGFBP1 induced FAPα expression by enhancing the paracrine FGF2/FGFR1/ERK1/-2/EGR1 signaling pathway in HSCs." (PMID 35951441, 2022). "A phase 1/2 study (NCT01752920) of another pan-FGFR inhibitor, ARQ087, included one ACC patient with FGFR1 gene amplification who experienced disease stabilization for 3.5 years with a maximum tumor reduction of 20% post-treatment." (PMID 35583844, 2022). "Studies have shown that inhibition of FGFR1 significantly reduces tumor cell numbers in FGFR1-amplified NSCLC." (PMID 36431263, 2022). "Fibroblast growth factor receptor (FGFR) is often overexpressed in HNC, especially FGFR1, which is more commonly altered in the larynx and hypopharynx primary tumor locations." (PMID 35052649, 2022). "We show that in NPC, it is synthesized by tumor cells and stimulates angiogenesis via FGFR1 on the ECs." (PMID 35985991, 2022). "FGFR1 expression was low in most tumor samples, but the expression patterns of other genes in the 8p11-12 amplicon were heterogeneous." (PMID 35402233, 2022). "FGFR1 is expressed on a number of cells, inclusive of endothelial and stromal/interstitial cells, both within the tumour and throughout the host." (PMID 35152467, 2022). "In this context, it is noteworthy, that while PA, DNT and RGNT share frequent FGFR1 hotspot alterations they represent epigenetically distinct tumor entities with separate methylation clusters." (PMID 35018490, 2022). "Regorafenib, a multi-kinase inhibitor, inhibits several numbers of protein kinases implicated in tumour growth (KIT, RET, RAF-1, and BRAF p38 MAP kinase), metastasis (PDGFR- and FGFR1), and tumour angiogenesis (VEGFR-1, -2, and -3)." (PMID 36614133, 2022). "In contrary, in one of three dovitinib responders in the NCT01861197 trial, low FGFR1–3 mRNA levels and a high FGFR1 amplification level in the tumor were reported." (PMID 35402233, 2022).
tumor (continued). "In previous studies, dysregulation of FGFR1 signaling was related to tumor progression and tumor immune therapeutic resistance." (PMID 36676646, 2022). "Given that the VAF of both the FGFR1 and PTPN11 variants were nearly identical in the tumor tissue suggesting that the variants co‐exist in the tumor cells, it is possible that the FGFR1 mutation that initiated the clonal expansion and tumor progression." (PMID 35778969, 2022). "Fibroblast growth factor receptor 1 (FGFR1) is frequently upregulated in ESCC tumor tissues and cell lines." (PMID 35216506, 2022). "Medium and high tumor FGFR1 mRNA expression was reported in 27–60% of patients with Sq-NSCLC, and 55 of 118 (47%) Sq-NSCLC tumors had FGFR1–3 mRNA overexpression." (PMID 35402233, 2022). "Expression of FGFR1 was observed in the cytoplasm and membrane of tumor cells and staining intensity was homogenous throughout the tumor tissue." (PMID 35018490, 2022). "In this location, histopathology and radiology are of limited interest, but molecular data (methyloma, 1p and FGFR1 status) represent important tools differentiating these two mitogen-activated protein kinase (MAPK) altered tumour types, PA and DLGNT." (PMID 36264505, 2022). "Surufatinib is a drug that targets tumor angiogenesis (VEGFR and FGFR1) and tumor immune evasion (CSF-1R)." (PMID 35874717, 2022). "Various studies have shown that PTK7 and FGFR1 are significantly upregulated in ESCC tumor tissues and cell lines." (PMID 35216506, 2022). "Genetic and pharmacological targeting the FGF-2/FGFR1 signaling or depletion of pericytes obliterates tumoral CXCL14 expression in FGF-2–expressing tumor–bearing mice." (PMID 35439170, 2022). "FGF2 regulates tumour growth and migration in vitro and in xenograft models, not only by activating FGFR1 signalling, but also through oestrogen receptor (ER) signalling." (PMID 35193394, 2022). "Several activating mutations in different FGFR isoforms such as FGFR1 N546K, FGFR3 K650E, and FGFR4 G388A have been reported in ES samples as possible enhancers of tumor aggressiveness in comparison with the FGFR wild-type tumors." (PMID 36430263, 2022). "Tissue sections isolated from tumors treated with FGFR1i revealed a lesser extent of FGFR1 expression, mostly towards the periphery of the tumor." (PMID 33596850, 2021). "Members of the fibroblast growth factor receptor family of kinases (FGFR1–4) are dysregulated in various cancers, increasing cell proliferation and survival of tumor cells." (PMID 34768978, 2021). "FGF2 and activation of FGFR1 regulate immunity in the tumour microenvironment by affecting macrophage programming." (PMID 33655556, 2021). "AZD4547 selectively targets the FGFR1-3 tyrosine kinases and inhibits tumor growth in an FGFR-driven human tumor xenograft model." (PMID 34638374, 2021). "In order to assess the possible role of each drug on brain metastasis, eight protein/gene effectors known to have a more important role in brain metastasis than in primary tumours were considered: FGFR1; Ki-67, ROBO1; S100A7; S100B; SIRT1; SLIT2; and VEGFA." (PMID 33659043, 2021). "RNA interference of FGFR1 expression in Ewing sarcoma lines blocked proliferation and completely suppressed xenograft tumour growth." (PMID 33655556, 2021). "Herein, we demonstrate that enhanced expression of FGFR1 is sufficient to drive tumor recurrence following induction of MRD by T-DM1." (PMID 33479246, 2021). "The combination of fulvestrant and palbociclib with FGFR-targeting lucitanib enhanced tumor inhibition of FGFR1-overexpressing cancer cells." (PMID 34831231, 2021). "Studies of selective FGFR inhibitors reported tumor cell lines with high FGFR1/3 expression to be more sensitive to the FGFR1/3 inhibitor PD 173074." (PMID 34933671, 2021). "We observed only a modest partial inhibition of CCL5 reporter activity, suggesting that FGFR1-independent signaling plays a major role in tumor cell-induced CCL5 expression in mammary fibroblasts." (PMID 33868996, 2021).
tumor (continued). "We found FGFR1 transcript to be selectively elevated in cells from spindloid tumours when compared to all other tumour types and normal mammary gland, while FGFR2 and FGFR3 were not modulated and FGRF4 was undetectable (not shown)." (PMID 33772015, 2021). "The ability of MET and FGFR1 signalling to compensate for one another in support of tumour growth has been identified in various human cancers." (PMID 33772015, 2021). "We demonstrate that combination of zotatifin with PI3K or AKT inhibitors, which aim at vertical inhibition of the PI3K/AKT/eIF4F pathway, induce synergistic anti-tumor activity across many of these FGFR1/2 and HER2 driven tumors." (PMID 34900714, 2021). "Accordingly, a reduced rate of MM cell proliferation paralleled by a reduced FGFR1 activation occurred in vivo in both endothelial and tumor cells when PTX3 was overexpressed and accumulated in the extracellular matrix of grafted tumors." (PMID 34066669, 2021). "Of note, FGFR2 expression was highest in the patient’s tumor than in all other tumors from the TCGA cohort (log2 fold change = 2.01), whereas the expression levels of different tyrosine kinases, including FGFR1, 3, and 4, was in the range of the other samples." (PMID 34480077, 2021). "FGFR1 can be activated to influence the proliferation, survival, migration and differentiation of tumor cells." (PMID 34899853, 2021). "Collectively, this indicates that when the FGFR1 is overexpressed, the ERK pathway becomes dispensable, and the tumor cells rely solely on the FGFR1/Akt pathway." (PMID 34267282, 2021). "Fibroblast growth factor receptors (FGFR1-4) are tyrosine kinase receptors (TKIs) associated to cell survival, migration, and angiogenesis, and FGFR1 activation by FGF in an autocrine loop can drive tumorigenesis of multiple tumor types, including lung cancer." (PMID 34267282, 2021). "FGFR1 was significantly overexpressed in late tumor stage (p = 0.05) and node-positive patients (p = 0.04)." (PMID 34722544, 2021). "Colocalization of FGF2 in the nucleus and FGFR1 in the perinuclear region of mesenchymal tumor cells is dependent on co-translocation of syndecan-1." (PMID 34068954, 2021). "We next sought to evaluate the impact of FGFR1 expression on HME2 tumor growth and response to T-DM1." (PMID 33479246, 2021). "In detail, the MMTV-PyVT mice tumor gene microarray analysis identified fibroblast growth factor receptor-1 (FGFR1) as the topmost downregulated gene in the neoplasia stage." (PMID 34069906, 2021). "To study the extent of tumor penetration of FGFR1i-AuNS, we stained the treated tumor tissue sections with anti-FGFR1 biomarker because FGFR1i molecules lack autofluorescence properties." (PMID 33596850, 2021). "In this study, we assay TIC properties to directly investigate the role of Met in tumour initiation and identify FGFR1 signalling as a key convergent pathway with Met for the maintenance of TICs." (PMID 33772015, 2021). "Here, we presented multifunctional tumor‐targeted nanoparticles (NPs) that coloaded with autophagy inhibitor CQ and selective FGFR1 inhibitor PD173074." (PMID 33511016, 2021). "FGFR1 is an established modulator of tumor progression and resistance to currently used therapeutics." (PMID 33128042, 2021). "On average, the expression of FGFR1 mRNA appeared to be lower than that of FGFR4 in tumor tissue compared to peritumoral tissue." (PMID 33119860, 2021). "All variants found in tumor 2 were also observed in cell 2 (two variants of PIK3CA and one of FGFR1)." (PMID 33917394, 2021). "Making use of our previously published scRNA-seq data, we further found that FGFR1 expression is present among various subpopulations whereas FGFR3 is enriched in undifferentiated tumor cells." (PMID 34046693, 2021). "Specifically, compounds 151 and 152 reduced the tumor volume by triggering apoptosis of both tumor and tumor-associated endothelial cells via inhibition of angiogenesis-related receptor tyrosine kinases including VEGFR2, FGFR1, and EGFR." (PMID 34885716, 2021).
tumor (continued). "The contribution of miR-15a-5p/FGFR1 to the tumor-promoting effects of CERS6-AS1 in PDAC cells was assessed employing rescue experiments." (PMID 33581689, 2021). "We find that in TNBCs with mesenchymal signatures, MET participates in a compensatory interplay with FGFR1 to regulate tumour-initiating cells (TICs)." (PMID 33772015, 2021). "Untreated tumor tissue sections showed a generalized and diffuse cytoplasmic reaction throughout the specimen, reflecting high expression levels of FGFR1." (PMID 33596850, 2021). "Resistance is typically associated with amplification of MET or FGFR1, supporting the ability of MET and FGFR to activate similar key signalling pathways required for tumour progression." (PMID 33772015, 2021). "Elevated level of FGFR1 has been observed in various tumor types, like breast, lung, head or neck cancers." (PMID 34635096, 2021). "Taken together, circARVCF contributed to DDP resistance and promoted tumor cell proliferation, migration, and invasion in GC by regulating miR-1205 and FGFR1 expression." (PMID 34899853, 2021). "Recently, numerous studies have shown that FGFR1 can promote tumour progression and development by regulating signaling pathways and inducing cancer cell survival, proliferation and tumour angiogenesis." (PMID 33989301, 2021). "IHC and TUNEL assays in the tumor tissues displayed that GZD824 inhibits the FGFR1 activation and induces apoptosis in Ba/F3‐FGFR1 and Ba/F3‐FGFR1‐V561F xenograft models." (PMID 34114373, 2021). "We now demonstrate that FGFR1-driven methylation mediates suppression of miR-146b-5p, which leads to tumor development as a result of increased IRAK1 expression." (PMID 34906138, 2021). "We find that simultaneous inhibition of Met and FGFR1 activity abrogates properties of stemness and reduces TICs, hindering tumour progression." (PMID 33772015, 2021). "Genes of interest involved in tumor progression or uterine fibroids, from previous studies, FGFR1, CCND1, PCDH11X, VDR, NDRG2 and INPP4B, are indicated in the volcano plot." (PMID 33807176, 2021). "We previously generated the HC11/R1 cell line, which is driven by an inducible FGFR1 oncogene when stimulated with a B/B homodimerizer and capable of tumor growth in vivo." (PMID 34743736, 2021). "A recent study reported that 7.1% of all tumor types exhibited genetic alterations and that FGFR1 was involved in almost 50% of these alterations." (PMID 33989301, 2021). "We further identified that sensitivity to zotatifin in FGFR1/2 or HER2 driven tumor models is dependent on the activation state of the mTOR signaling pathway." (PMID 34900714, 2021). "Previous studies found that the expression of VEGF, FGFR1–4, and their receptors markedly affected tumor aggressiveness and prognosis; however, little research on how this affects HNSCC has been published." (PMID 34955687, 2021). "In summary, FGFR1–4 genomic alterations are highly diverse and present at low to moderate frequencies across many tumour types." (PMID 33268819, 2021). "In summary, we show that FGFR1 alterations occur in a wide spectrum of known tumor entities with overlapping histologic features." (PMID 32859279, 2020). "This subpopulation differentially expresses genes that have been shown to be tissue-reparative (Hmox1, Gas6) and tumor-promoting (Pf4, Fgfr1, and Nrp2)." (PMID 33072601, 2020).
tumor (continued). "Macrophages were the only immune cell population in tumours to abundantly expression FGFR1 or 2, and in tissue culture, we showed that tumour cells can induce the expression of FGFR1 and 2 in BMDM." (PMID 32792542, 2020). "We would also measure FGFR1, LepR, and phospho-Jak2 protein expression in tumor tissue since one shortcoming of our study is that many of our correlations involve mRNA." (PMID 33019728, 2020). "The study showed how the inhibition of FGFR1 decreased tumor cell viability, thus highlighting the importance of environmental growth factors in developing tumor escape towards RTK inhibitors." (PMID 33352931, 2020). "While cabozantinib effectively inhibited tumor growth in NT xenografts, OV FGFR1 PDX grew exponentially in the presence of cabozantinib, at rates similar to the untreated tumors." (PMID 31963871, 2020). "More importantly, tumor cell lines with high FGFR1/3 expression were more sensitive to FGFR inhibitor PD173074, especially in BRCA, LIHC, LUSC, and OV." (PMID 32596330, 2020). "Erdafitinib, an inhibitor of FGFR1–4, resulted in tumor shrinkage in an adrenal carcinoma patient with the FGFR3-TACC3 fusion." (PMID 31987043, 2020). "The H-score of FGFR1 was only weakly correlated in stromal cells and tumor cells (r = 0.256, P < 0.001)." (PMID 32326908, 2020). "In this study, we successfully demonstrated the feasibility of sWGS (plasma-Seq) for detecting genome-wide structural genomic anomalies, including FGFR1 gene amplification, as well as estimating tumor content in the plasma of mBC patients." (PMID 32517171, 2020). "BRAF V600E mutations were linked to GG with CD34 expression, FGFR1 mutations to DNT, MYB alterations to AG and also IDG and PRKCA fusions to PGNT, suggesting the possibility to also develop a genetically driven tumor classification scheme for LEAT." (PMID 32151273, 2020). "FGFR1 staining exhibited cytoplasmic patterns with occasional weak nuclear patterns and was uniform in most tumor areas." (PMID 32326908, 2020). "FGF-2 and its receptor FGFR1 can enhance tumor cell proliferation and migration by acting on stromal cells and cancer cells." (PMID 33213510, 2020). "Fibroblast growth factor receptor (FGFR) 1, which encodes for FGFR1 is generally reported to be overexpressed in CRC and promotes cell proliferation, cell survival, and angiogenesis, resulting in tumor development." (PMID 32825052, 2020). "Elevated LepR mRNA and FGFR1 mRNA were positively correlated in primary breast tissue (R = 0.51), in areas adjacent to the tumor (R = 0.62), and to a lesser extent in normal tissue (R = 0.46)." (PMID 33019728, 2020). "In this study, we identified fibrosis and FGFR1 expression as new prognostic markers to predict tumor recurrence and overall survival, respectively." (PMID 32171280, 2020). "First, AKT inhibitors should be used to inhibit FGFR1‐ or miR‐3116 inhibitor‐mediated tumour cell growth in vitro and in vivo." (PMID 32181582, 2020). "Of note, the weight gain and the adipocyte diameter positively correlated with (i) the levels of FGF1, (ii) FGFR1 activation in tumor cells, and (iii) estrogen-independent tumor growth." (PMID 33081025, 2020). "In the original report, a cohort of 33 HGG were screened for duplication of the FGFR1 region encoding the TKD, revealing only one tumor (diagnosed as anaplastic oligoastrocytoma, WHO grade III) that had progressed from a grade II tumor." (PMID 32085805, 2020). "In one tumor (RGNT #4), the FGFR1 p.N546K mutation was present at 37% allele frequency whereas the second mutation (p.K523T) was subclonal and present at 8% allele frequency." (PMID 32859279, 2020).